RNU6-55P (RNA, U6 small nuclear 55, pseudogene)
Synonyms: RNU6-55
Gene: Small nuclear RNA gene on chromosome 13 (18,869,185 to 18,869,291, reverse strand). Ensembl gene ENSG00000223024.
Homologues: Orthologues: chimpanzee U6 (100% identical), macaque U6 (95% identical), dog U6 (72% identical), mouse Gm54642 (60% identical), mouse Gm22279 (59% identical), rat LOC120101210 (58% identical). Paralogues in human: RNU6-954P (99% identical), RNU6-316P (98% identical), RNU6-1193P (95% identical), RNU6-1269P (95% identical), RNU6-368P (95% identical), RNU6-538P (95% identical), RNU6-1320P (94% identical), RNU6-599P (94% identical), U6 (94% identical), U6 (93% identical), RNU6-821P (90% identical), RNU6-798P (88% identical), and 1289 more.